ALB (albumin)
Diseases named in the same sentence as ALB in open-access papers (continued):
Sharing a sentence is not in itself a finding about the gene and the disease.
COVID-19 (continued). "However, many studies and meta-analyses have been performed that have proposed different biomarkers for poor prognosis for COVID-19, including C-reactive protein (CRP), albumin, procalcitonin, neutrophil-to-lymphocyte ratio, apolipoproteins, D-dimer, and ferritin." (PMID 36006278, 2022). "Albumin levels along the in-hospital stay of confirmed COVID-19 patients were not documented." (PMID 35160039, 2022). "However, COVID-19 patients with elevated ferritin presented a significant increase of APPs, hepatic parameters (except for ALP activity), and LDH with a contemporaneous decrease of albumin, HDL- and LDL-cholesterol concentrations." (PMID 34728695, 2021). "Additionally, high-sensitivity C-reactive protein–albumin ratio (HsCAR) and low prognostic nutritional index (PNI) and the ratio of interleukin (IL)-6 to IL-10 were reported to be related to the prognosis of COVID-19 patients." (PMID 34217339, 2021). "Hospitalized COVID-19 patients demonstrated statistically significantly higher concentrations of CRP (48 [9.0–81.0] vs. 1.9 [1.0–5.5], p < 0.001) and creatinine (91.8 [85.5–97.2] vs. 71.0 [61.0–80.0], p = 0.022) and lower albumin (39.1 [37.7–42.1] vs. 44.0 [42.0–46.0], p = 0.010)." (PMID 34943125, 2021). "In patients with COVID-19, the ROC analysis showed positive predictions of albumin and hematocrit, but negative predictions of C-reactive protein (CRP), procalcitonin (PCT), lactate dehydrogenase (LDH), hydroxybutyrate dehydrogenase (HBDH), and erythrocyte sedimentation rate." (PMID 34859002, 2021). "The ROC curve results indicated that lower LDH, TP, CRP and higher ALB could predicted patients with COVID-19 whose nucleic acid would turn negative within 14 days." (PMID 33663273, 2021). "The structure of serum albumin in complex with dexamethasone reveals why the drug may not always help COVID-19 patients." (PMID 33063792, 2020). "Indeed, increased albumin concentration in CSF was detected in up to 50% of individuals affected by COVID-19 when compared to non-infected controls, and several autopsy studies found increased fibrinogen leakage in different brain regions of COVID-19 patients compared to SARS-CoV-2 naïve patients." (PMID 37875964, 2023). "Moreover, the performance of the combination of the ESR, NEU, CRP, Albumin, RBC, Chlorine, and RDW features in detecting infected patients being higher than their individual performance indicates a high level of confidential information about COVID-19 among these blood features." (PMID 35808317, 2022). "This information is in line with the fact that COVID-19 is characterized by the release of potent vascular permeability mediators such as arachidonic acid metabolites, IL-8, and monocyte chemoattractant protein-1 (MCP-1), all of which might contribute to the transvascular leakage of albumin." (PMID 34683480, 2021). "Moreover, the percentage of HLA-DR+CD38hi CD8+ T cells was found to have positive correlations with aspartate transaminase (AST) and total bilirubin (TB) in COVID-19 patients (R=0.397, P<0.0001; R=0.398, P<0.0001), and a strong negative correlation with albumin (R=−0.481, P<0.0001)." (PMID 34567001, 2021). "However, this may be a result of our study restricting the definition of mortality to only include in-hospital mortality whereas the prior studies comparing albumin levels and COVID-19 outcomes did not define restrictions on mortality." (PMID 33725003, 2021). "In addition, the use of perfusion-only scans is unlikely to be of any benefit if COVID-19 is suspected, as the COVID-19 response might alter the macroaggregated albumin distribution." (PMID 32312852, 2020). "Additional variables with predictive potential for the Brixia score included male sex, a lack of COVID-19 vaccination, lactate dehydrogenase (LDH), albumin levels, and severe infection." (PMID 40423360, 2025).
COVID-19 (continued). "According to the present meta-analysis, COVID-19 patients admitted to the ICU and COVID-19 non-survivors had a lower PLT counts, as well as lower hemoglobin and albumin concentrations." (PMID 36747045, 2023). "In samples from COVID-19 patients, we observed visually similar EPR spectra and parameters that were close to those of 3-Maleimido-PROXYL/DMSO (no albumin available)." (PMID 36982882, 2023). "Compared with patients without AKI, COVID-19 patients with AKI in our study had lower platelet counts, lymphocyte counts, albumin levels and serum calcium levels but had higher leukocyte counts, neutrophil counts and serum potassium levels." (PMID 35656097, 2022). "Compared with patients without AKI, COVID-19 patients with AKI had lower platelet counts, lymphocyte counts, albumin levels and serum calcium levels but had elevated leukocyte counts, neutrophil counts and serum potassium levels." (PMID 35656097, 2022). "Other factors considered to be beneficial against COVID-19 are non-neutralizing anti-spike antibodies, antithrombin, alpha-1 antitrypsin, ACE-2, albumin and others." (PMID 35852992, 2022). "We also confirmed the presence of increased damage in the post-COVID-19 airway by measuring DPP4 and two markers of damage not analyzed by Olink, albumin and lactate dehydrogenase (LDH)." (PMID 35151371, 2022). "Among COVID-19 patients without comorbid conditions, sodium, potassium, CRP, ferritin, total protein, and albumin showed significant changes." (PMID 35165642, 2022). "Severe patients with COVID-19 were suggested to have higher levels of CRP, D-dimer, and LDH and a lower level of albumin than non-severe patients." (PMID 34021206, 2021). "In this study, we retrospectively analyzed the clinical data of symptomatic patients with COVID-19, logistic regression analysis revealed patients whose nucleic acid turned negative within 14 days had lower LDH, CRP and higher ALB." (PMID 33663273, 2021). "In both admission and follow-up evaluation, a more significant association was observed with CRP-related inflammatory biomarkers such as CRP/albumin ratio and CRP/lymphocyte ratio rather than NLR and PLR, which are widely used in the literature, in showing the severity of COVID-19." (PMID 38298278, 2024). "In both admission and follow-up evaluation, a more significant association was observed with CRP-related biomarkers such as CRP/albumin ratio and CRP/lymphocyte ratio rather than NLR and PLR, which are widely used in the literature, in showing the severity of COVID-19." (PMID 38298278, 2024). "However, COVID-19-negative plasma pool did not produce any purple spots at RBD protein, nucleocapsid protein, or albumin positions." (PMID 37589006, 2023). "The values of the rest of the parameters, such as albumin, TB, LDH, and D-dimer, were slightly higher in the initial stage of the infection but the decreasing trend was low; hence, they did not have a significant impact on the Ct value and COVID-19 severity." (PMID 36968904, 2023). "Furthermore, the concept of a relationship between low serum albumin and more severe disease progression has previously been found to exist in ARDS independent of COVID-19." (PMID 34367693, 2021). "Moreover, in a meta-analysis of 128 studies, the relative risk of elevated liver function tests in severe compared with non-severe COVID-19 patients were 1.76 (ALT), 2.30 (AST), 2.31 (GGT), and for decreased albumin levels a value of 2.65." (PMID 34287285, 2021). "However, when compared with the serum level of albumin, the PNI had a higher AUC for prediction of COVID-19 severity but was not significant using the Concordance Index (C-Index)." (PMID 33521032, 2020). "Moreover, COVID-19 patients with ARDS had lower levels of lymphocytes (0.53 × 109 /L, IQR: 0.40–1.07 vs 1.03 × 109 /L, IQR: 0.78–1.52) and serum albumin (ALB: 29.4 g/L, IQR: 26.5–33.0 vs 33.7 g/L, IQR: 29.9–36.5) than COVID-19 patients without ARDS." (PMID 33334314, 2020).
COVID-19 (continued). "Interestingly, our results revealed an albumin-predominate urine protein profile whether the patients had AKI or not, suggesting that the proteinuria in COVID-19 is predominantly of glomerular origin." (PMID 37479685, 2023). "We found that ALB, NLR, CD4/CD8 ratio, and eosinophil count were effective and efficient predictors of viral shedding duration, which might help discharge management for patients with non-severe COVID-19." (PMID 36620263, 2022). "Therefore, our findings suggest that the LDH, ALB and CRP are of practical value in identifying patients with COVID-19 whose nucleic acid could turn negative during the quarantine period (14 days)." (PMID 33663273, 2021).
diabetic nephropathy (582 papers, 2005 to 2026). "This work presents, for the first time, a novel cross injection analysis (CIA) system for the simultaneous multi-determination of key biomarkers associated with diabetic nephropathy-namely, albumin, creatinine, and glucose-within a single analytical run." (PMID 42197325, 2026). "The overactivation of (P)RR is associated with several diseases such as heart failure, diabetic nephropathy, albumin overload, and liver fibrosis." (PMID 40650317, 2025). "Diabetic nephropathy (DN), or diabetic kidney disease, is “a syndrome characterized by the presence of pathological quantities of urine albumin excretion, diabetic glomerular lesions, and loss of the glomerular filtration rate (GFR) in diabetics”." (PMID 38993632, 2024). "Elevated level of urine albumin concentration is a hallmark of diabetic kidney disease and is associated with multiple cardiovascular and metabolic diseases." (PMID 39340798, 2024). "It is reported that physical activity is associated with improved renal function and reduced risk of diabetic nephropathy, as shown by an increase in the glomerular filtration rate and a decrease in the urinary albumin-creatinine ratio." (PMID 39569233, 2024). "A study involving 682 Chinese patients with type 2 diabetes revealed that an elevated TyG index was an independent risk factor (OR 1.91, P = 0.001) for diabetic nephropathy, defined as an albumin excretion rate > = 30 mg/day or > = 20 μg/min." (PMID 38664793, 2024). "Six significant mediators were detected on the associations of lifestyle score with risk of the composite microvascular complications and diabetic kidney disease, namely, albumin, HDL-C, triglycerides, apolipoprotein A, CRP, and HbA1c." (PMID 36626356, 2023). "Diabetic nephropathy (DN) or diabetic kidney disease is a syndrome characterized by the presence of pathological quantities of urine albumin excretion, diabetic glomerular lesions, and loss of glomerular filtration rate (GFR) in diabetics." (PMID 37990213, 2023). "This study focuses on the potential of urine albumin estimation as an early diagnostic tool for diabetic nephropathy among patients in central India." (PMID 37868453, 2023). "Diabetic kidney disease was originally defined by Mogensen 40 years ago as a progressive kidney disease in diabetic patients, beginning with the loss of small amounts of albumin in the urine (30-300 mg per day)." (PMID 37545693, 2023). "A clinical study has also shown that lower serum albumin levels are associated with a higher risk of CVD events in patients with diabetic kidney disease." (PMID 37608840, 2023). "Diabetic nephropathy (DN) or diabetic kidney disease is a syndrome characterized by the presence of pathological amounts of urinary albumin excretion, diabetic glomerular lesions, and loss of glomerular filtration rate (GFR) in diabetics." (PMID 37990213, 2023). "Albuminuria is considered a risk factor for various diseases, among which diabetic nephropathy is known to be closely related to urinary albumin concentration." (PMID 35955470, 2022). "Increase glycated albumin values have been associated with diabetic nephropathy, neuropathy, and cardiovascular complications." (PMID 35328045, 2022). "Multivariate linear regression analysis showed that sex, age, BMI, diabetic nephropathy, as well as albumin at baseline were independently associated with albumin at 1 year." (PMID 35166186, 2022). "Our findings of significant inverse associations between serum albumin and all-cause mortality indicate that patients with higher serum albumin levels had fewer diabetic-related morbidities (for example, diabetic nephropathy)." (PMID 35807807, 2022). "It seemed that in diabetic kidney disease patients with albuminuria, glomerular filtration rate and albumin excretion rate were independently associated with DR." (PMID 36388275, 2022).
diabetic nephropathy (continued). "Higher levels of both TNFR1 and TNFR2 were associated with prevalent diabetic kidney disease, as well as with worsened kidney function and higher urinary albumin/creatinine ratio." (PMID 35328704, 2022). "Multivariate linear regression analysis showed that sex, age, BMI, diabetic nephropathy, as well as albumin at baseline were independently associated with albumin at 1 year after PD." (PMID 35166186, 2022). "Increased levels of albumin in turn predict the risk for diabetic nephropathy, including loss of kidney function and ESRD." (PMID 36579508, 2022). "Several cross-sectional studies reported that VAI is an independent risk factor for excess urinary albumin excretion and diabetic nephropathy, and CVAI is closely associated with the prevalence of cardiovascular diseases and diabetic nephropathy." (PMID 35209907, 2022). "Salt added to food increases urinary albumin excretion which significantly increases risk of cardiovascular events and progression of diabetic nephropathy." (PMID 36067082, 2022). "Diabetic nephropathy is a condition characterized by the uncontrolled secretion of urine albumin, loss of glomerular filtration rate, and glomerular lesions." (PMID 36363561, 2022). "Those authors suggested that being vegetarian, having diabetic nephropathy, having alcoholic or nonalcoholic fatty liver disease and presenting long bypass limb length were possible causes of albumin deficiency." (PMID 34644766, 2021). "In patients with T2DM, PON1 alleles 54L, -162 A and -1074 G, which lead to the lower PON1 activity, were significantly associated with the higher urinary albumin loss indicating the diabetic nephropathy." (PMID 33670025, 2021). "The associations between cadmium and lead and diabetic kidney disease (albumin excretion >30 mg/24 h and/or creatinine clearance <60 mL/min/1.73 m2) were determined using multivariate logistic regression." (PMID 32751456, 2020). "Alterations in albumin excretion are considered as the hallmark for prediction of the onset and progression of diabetic nephropathy." (PMID 32121033, 2020). "Guidelines also advocate regular urinary testing for albumin/creatinine ratio (ACR) since there is extensive evidence that albuminuria is a strong risk factor for progression of diabetic kidney disease (DKD)." (PMID 31915892, 2020). "Based on this model, we explored the potential effect of PU on diabetic nephropathy and its underlying mechanism, proving that PU provides potential renal protection, which is characterized by inhibition of the urine albumin, serum creatinine, and BUN levels." (PMID 32456088, 2020). "High eGFR, high albumin, and advanced age significantly decreased the risk of renal events, whereas high systolic blood pressure, male sex, diabetic nephropathy, calcium channel blockers, activated carbon product, sodium bicarbonate, and higher C.E.R.A." (PMID 30291472, 2019). "Clinical findings of diabetic nephropathy include a decline in estimated glomerular filtration rate (eGFR) as well as a progressive increase in urinary albumin excretion, associated with an increase in blood pressure and subsequent risk of renal failure." (PMID 31660880, 2019). "In diabetic kidney disease (diabetic nephropathy) glomerular cells become damaged resulting in increased albumin loss." (PMID 29301371, 2018). "As expected serum albumin was strongly associated with better renal function only in GenodiabMar cohort, due to a higher prevalence and a more severe diabetic nephropathy in this population." (PMID 30323304, 2018). "The increase in urinary albumin excretion, one of the marked renal pathological features in diabetic nephropathy, is caused by mesangial expansion due to accumulation of extracellular matrix components." (PMID 28767064, 2017). "Impaired albumin reabsorption by proximal tubular epithelial cells (PTECs) has been highlighted in diabetic nephropathy (DN), but little is known about the underlying molecular mechanisms." (PMID 29203863, 2017).